PIK3CB (phosphatidylinositol-4,5-bisphosphate 3-kinase catalytic subunit beta)
Diseases named in the same sentence as PIK3CB in open-access papers (continued):
Sharing a sentence is not in itself a finding about the gene and the disease.
tumor (63 papers, 2012 to 2026). "Sanger sequencing showed that MTC-22 cells harboured mutations in ARID1A (Q1346*) and PIK3CB (E1051K), both identical to those seen in the patient’s tumour tissue." (PMID 38573494, 2024). "For instance, the PLAGL2 and the PIK3CB were identified as key hub gene within the regulatory network that significantly associated with tumor immune infiltration and sensitivity of chemotherapeutic drugs for cancer." (PMID 38971948, 2024). "What is more, ctDNA genomic alterations such as KEAP1 and PIK3CB were also in accordance with the difference tendency in tumor tissue samples, indicating that the plasma ctDNA can potentially reflect tumor-derived genomic mutation." (PMID 35155229, 2022). "We observed, in selected models, synergistic effects and complete tumor regressions by the combination of cetuximab with everolimus—for example, in model Co11192-259 with a mutation in PIK3CB." (PMID 34885128, 2021). "A mutation in the PIK3CB kinase domain (D1067V), was shown to occur in several tumour types at low rates." (PMID 30544563, 2018). "Moreover, point mutations in ARID1A and PIK3CB genes detected in the patient’s tumour tissue were present in MTC-22 cells." (PMID 38573494, 2024). "Besides mutations in PIK3CA and PIK3CB genes, inactivating events also occur in tumor suppressors such as PTEN." (PMID 34298731, 2021). "The paradoxical decline of both proteins Akt and PTEN in FAK KD stromal cells could be explained by ablation of p110beta protein (also known as Pik3cb) within a rescue mechanism as observed in PTEN-deficient tumours." (PMID 32155953, 2020). "Moreover, characteristic point mutations—one in ARID1A, which encodes the AT-rich interaction domain containing protein 1A, and the other in PIK3CB, which encodes the catalytic subunit of phosphoinositide 3-kinase—were seen in the patient’s tumour tissue and retained in MTC-22 cells." (PMID 38573494, 2024). "Our data suggest that although inactivation of either Prex2 or Pik3cb has little impact upon tumor initiation or progression, both sensitize to MEK1/2 inhibition." (PMID 39636745, 2025). "KEAP1 and PIK3CB alterations were also in accordance with the difference tendency in tumor tissue samples." (PMID 35155229, 2022). "Aberrant expression of PIK3CB has been found in multiple cancers and is involved in tumor cell growth, metabolism, angiogenesis, metastasis, and multidrug resistance." (PMID 35936737, 2022). "We found that in three of the four cases with low CDKN2A mRNA expression but strong p16 protein staining, the tumor harbors either PIK3CA mutation, PIK3CB amplification or loss of PTEN gene (case B6, NB7, NB8)." (PMID 34948172, 2021). "Intriguingly, genomic gain in PIK3CA or PIK3CB were associated decreased CD8 T cells, Th1 cell but increased Th2 cells infiltration in multiple tumor types, which was similar to what we observed for PTEN loss." (PMID 33874915, 2021). "Mutations targeting catalytic class I PI3K isoforms are only associated to PIK3CA catalytic isoform, while in the other class I catalytic isoforms PIK3CB, PIK3CD, and PIK3CG tumor associated mutations are very rare." (PMID 32033478, 2020).
tumor (continued). "Mutation of PIK3CB, as the catalytic subunit in the PI3K signalling pathway, drives tumour cell growth and migration." (PMID 32419250, 2020). "Optimized siRNAs targeting KRAS impaired colon cancer growth in vivo while combinatorial inhibition of KRAS and PIK3CA/PIK3CB significantly improved tumor control compared to single agents alone, demonstrating that targets can be effectively multiplexed." (PMID 31681559, 2019). "CNA driver genes such as PIK3CB lost in 9 tumours, PIK3R1 and AKT amplified in 6 and 4 tumours respectively are linked with 58, 57 and 53 KEGG pathways underlining the tremendous effects of individual gene losses and gains." (PMID 28486536, 2017). "Treatment of PTEN-mutant tumor xenografts by intratumor (i.t.)injection of PIK3CB siRNA (siPIK3CB) or by expression of doxycycline (doxy)-inducible PIK3CB shRNA was markedly more potent than PI3Kβ inhibition." (PMID 27863432, 2016). "Since all vehicle- (liposome) treated samples showed an inflammatory neutrophil infiltration, it is possible that an action of PIK3CB siRNA in the tumor environment contributes to tumor growth deceleration." (PMID 27863432, 2016). "In most PTEN-mutant UBC cells, PIK3CB knockdown induced apoptosis and effectively led to tumor regression; PI3Kβ depletion was markedly more efficient than PI3Kβ inhibition." (PMID 27863432, 2016). "In breast cancer, circular RNA (circ_0001142) is also delivered from tumor cells to macrophages using exosomes as carriers, which regulates autophagy through the miR-361-3p/PIK3CB/PI3K/AKT pathway, inducing M2 polarization and further facilitating tumor proliferation and metastasis." (PMID 40612677, 2025). "Recent research indicates that endoplasmic reticulum (ER) stress enhances tumor cell exosome secretion, facilitates the transfer of circ_0001142 into macrophages, and modulates the miR‐361‐3p/PIK3CB pathway, thereby affecting macrophage autophagy and polarization in breast cancer." (PMID 39584047, 2024). "Moreover, both the patient’s tumour tissue and MTC-22 cells showed identical point mutations in the ARID1A and PIK3CB genes." (PMID 38573494, 2024). "By promoting tumor growth, high PIK3CB expression was related to the worse prognosis of LUAD." (PMID 37279937, 2023). "In elderly HGSOC, mutations in the genes that are involved in the Ras and or PIK3CA signaling pathways were detected in nine samples (15%), including the genes KRAS and BRAF (each one in 1 tumor); PIK3CB and MTOR (each one in 2 tumors); and NF1 (in three different samples)." (PMID 34944094, 2021). "Furthermore, PIK3CB is involved in tumor-related signaling pathways, and the decrease in H4K20 methylation in the PIK3CB promoter region was the most obvious." (PMID 34745943, 2021). "Furthermore, T cell exclusive phenotype is also observed in tumor with PI3K pathway activation or genomic gain in PIK3CA or PIK3CB." (PMID 33874915, 2021). "Interestingly, the CCP score was reported to increase early in grades 1 and 2 compared to CAHs, at the same stage of tumor development when PIK3CB mRNA levels are found to be increased in this study." (PMID 28002804, 2017). "siRNA delivery at the end of treatment might have been suboptimal due to the small tumor size; optimal PIK3CB depletion might have yielded additional effects." (PMID 27863432, 2016). "The gene mutations of the brain metastasis were not present in the extracranial tumours and, moreover, we identified three private gene mutations (PIK3CB M819L, PIK3CB Q818H, AHNAK2 L5292V) exclusively present in the meningeal lesion." (PMID 26554728, 2015). "This requires glucose uptake and energy sources for normal cellular response to stress and tumor growth, syndrome development, vascular changes, and megalocephaly (e.g., PIK3R1; PIK3CA; PIK3CG; PIK3CD; PIK3CB; PIK3R3; PIK3R2; PIK3R5; PIK3R6)." (PMID 41010006, 2025).
tumor (continued). "To validate the results from online database analysis, we examined the expression of PIK3CB and SP1 in a cohort of 40 paired GC and non-tumor tissues by qRT-PCR." (PMID 38356702, 2024). "The results of WGCNA showed that the turquoise and blue modules, which are highly related to the eutopic endometrial cell group and the ectopic endometrial cell group, all contained tumor related genes, such as UBC, UBA52, RPS27A, PIK3CB, IRS1, and CEACAM1." (PMID 33868805, 2021). "PIK3CB, phosphatidylinositol-4,5-bisphosphate 3-kinase catalytic subunit beta, is a major regulator of the PI3K/Akt pathway, and it takes part in the growth and metastasis of a variety of tumours." (PMID 32993645, 2020). "In particular, the mRNA levels of PIK3CB were shown to be higher in grade 1 endometrioid endometrial lesions when compared to complex hyperplasias and remained high in higher grades as well as in NEEC tumours." (PMID 30544563, 2018). "However, our results showed that neither CEA nor PIK3CB levels were affected by tumor stage, tumor size, lymph node metastasis or distant metastasis." (PMID 37861518, 2023). "Based on previous literature and our study, we speculated that psoralen inhibited the proliferation and migration ability of tumor cells, promoted apoptosis, and blocked the cell cycle by reducing the expression levels of four genes: JAK2, PIK3CA, PIK3CB, and PIK3CG." (PMID 36065261, 2022). "More importantly, we reveal a relevant mechanism that PIK3CD, but not PIK3CA and PIK3CB, is transcriptionally regulated by the pro‐inflammatory IL2/JAK3/STAT5 axis and tumor‐infiltrating immune cells such as lymphocytes." (PMID 38545256, 2024). "When it came to alterations of several genes such as KEAP1 and PIK3CB, the tendency of discrepancy was unanimous in MVI/NMVI to recurrence/non-recurrence comparison, not only in tumor tissue but also in ctDNA analysis." (PMID 35155229, 2022).
infection (6 papers, 2017 to 2025). The state of being infected such as from the introduction of a foreign agent such as serum, vaccine, antigenic substance or organism. "PIK3CB can also activate neutrophils during injury or infection." (PMID 40650045, 2025). "From our results, the PIK3CB gene expression was down-regulated after the infection of CHv." (PMID 28903751, 2017). "In addition, the PI3K-Akt signaling pathway-related genes were expressed at lower levels in SFTSV infection 24 and 48 h, for example, GP1BA, PIK3CA, PIK3CB, AKT3, PRKG1, and PRKG2." (PMID 37211158, 2023). "The phosphatidylinositol 4,5-bisphosphate 3-kinase catalytic subunit beta isoform (PIK3CB) is an isoform of the catalytic subunit of phosphoinositide 3-kinase beta, which participates in several signaling pathways related to immune processes at the site of injury or infection." (PMID 38473885, 2024). "Using an overexpression experiment, Fung showed that JNK/MAPK8 participated in coronavirus–host interaction, so silencing lncRNA−MSTRG.16919.1 may affect the expression of SKIV2L2, JAK2, PIK3CB and MAPK8 proteins and then regulate the infection of MDBK cells by BHV−1." (PMID 36298658, 2022).
PIK3CB also shares sentences with these, for which no sentence is quoted: colon carcinoma (3 papers); bacterial infection (2); head and neck cancer (2); hepatitis B (2); subarachnoid haemorrhage (2); type 2 diabetes mellitus (2); acute myeloid leukemia (1); adenocarcinoma (1); Alzheimer disease (1); anaplastic cancer (1); Arrhythmia (1); Azoospermia (1); breast invasive ductal carcinoma (1); cardiovascular disease (1); colon adenocarcinoma (1); diffuse large B-cell lymphoma (1); esophageal cancer (1); gastric tumors (1); hereditary non-polyposis colorectal cancer (1); hyperthyroidism (1); leishmaniasis (1); leukemia (1); liver cancer (1); lung adenocarcinoma (1); lymphoma (1); Lynch syndrome (1); mantle cell lymphoma (1); metastatic melanoma (1); myeloid malignancies (1); neuroblastoma (1).
A further 13 diseases each share a sentence with PIK3CB in 1 paper.